CD4 (CD4 molecule)
Diseases named in the same sentence as CD4 in open-access papers (continued):
Sharing a sentence is not in itself a finding about the gene and the disease.
infection (continued). "In spite of the marked enhancing effect of ICAM-1 on HIV-1 binding and infection of T cell lines and primary CD4+ T cells, the virus fusion with primary CD4+ T cells appears to be only slightly (1.2-fold) enhanced by this adhesion molecule." (PMID 22970312, 2012). "Mice receiving one of the two groups CD4+ T cells on day 6 post infection were subsequently analyzed for fungal CFU in the brains at day 16 post infection)." (PMID 23110112, 2012). "The profile in B10 mice after PR8 infection was similar to that after NC infection, with clearly the majority of virus-specific CD4 T cells secreting IFN-γ." (PMID 22457834, 2012). "CD4 levels were depressed compared to baseline values at 10 days post infection in both wild-type SIVmne027 infected monkeys (by 9.6% and 60%, respectively)." (PMID 22531456, 2012). "Of the models that include a period of early infection, the percentage of new infections that occurs during this stage is between 4% and 28%, while between 20% and 51% of transmission results from individuals with CD4 cell count ≤200 cells/μl." (PMID 22802730, 2012). "In B10 mice, there was a shift in the predominant CD4 T cell-secreted cytokine from IFN-γ after infection to IL-2 after vaccination." (PMID 22457834, 2012). "Infections with both HIV-1JRCSF and HIV-1Bal isolates were associated with depletion of CD4+ T cells in the blood of humanized NSG mice." (PMID 22675567, 2012). "The highest viral load (8.89±3.23 log10 copies/ml) and the lowest CD4 count were observed in the 20 patients with anti-TB and anti-infection therapies." (PMID 23144953, 2012). "In tissues that were productively infected we evaluated the efficiency of this infection by measuring the release of p24 in the culture medium and by enumerating p24+ CD4 T cells with flow cytometry." (PMID 23236398, 2012). "After continuous passage of SIV mac239 in CEM x 174 cells, the resulting stock, which we here call SIV mac239 CEMx174, is CD4 independent for infection of human PBMCs, while remaining CD4 dependent in macaque PBMCs, as previously reported." (PMID 22830620, 2012). "Although ratios were variable for both groups of cats, these data suggested that FIV infection resulted in a decrease in the CD4+ T cell subset in blood." (PMID 22314004, 2012). "It should be noted however, that in other models - such as during M. tuberculosis infection - the PD-1/PD-L1 pathway has a direct effect on CD4+ T cells in preventing T cell-driven exacerbation of infection." (PMID 22319445, 2012). "VK627 and rTsE627K infection significantly reduced the numbers of CD4+ and CD8+ T cells at day 3 p.i. compared with the numbers detected in rVK627E and TsE627 groups." (PMID 22719870, 2012). "The proportion of human CD4+ T cells in the HIV-1-infected hNOK/B51Tg mouse gradually decreased from 2 weeks post-infection, whereas that in the uninfected hNOK/B51Tg mouse remained high." (PMID 22880104, 2012). "HIV-1 replicates preferentially in activated CD4+ T cells but these cells generally survive only for few days after infection." (PMID 22548060, 2012). "IL-1 and TNF-α have been shown to be produced by either the binding of gp120 to the CD4 molecules on mononuclear phagocytes or infection with HIV." (PMID 22242038, 2012). "The pattern of cytokine production by epitope-specific CD4 T cells in DR1 mice after NC infection was surprising." (PMID 22457834, 2012). "Semen is the principal vehicle for the sexual transmission of HIV, and in vitro semen can enhance the infection of physiologically relevant cell types, including primary macrophages and CD4+ T cells." (PMID 24832047, 2012). "The results showed that the percentage of CD4+ T cells in yellow cattle was always significantly higher than that in water buffalo from pre-infection to 7w post infection." (PMID 22414188, 2012). "While, treatment of such cells with CA-074Me at higher concentration attenuates the CD4-independent infection." (PMID 23304142, 2012).
infection (continued). "CD4 cells are critical to controlling infection with Pneumocystis, and CD4 responses have previously been shown to target Msg." (PMID 22788748, 2012). "Homozygosity for the high (H) repeat number BSSL genotype (HH) correlated with high CD4 cell numbers prior to infection (p = 0.007)." (PMID 22412885, 2012). "This suggests that the preferential infection of SupT1 cells can induce the virus to spare primary CD4+ T cells from infection and depletion." (PMID 22701517, 2012). "From the acute phase to the chronic phase, the immune response against the infection changes from the Th1-type to the Th2-type, and induces a significant increase of CD4+ CD25+ regulatory T cells, which have a broad immune suppression function." (PMID 22414188, 2012). "Clearance of the bacteria requires MHC-II restricted, SL3261-specific CD4+ T cells that become detectable at 7 days post-infection." (PMID 22738332, 2012). "Lastly, to more definitively establish infection-induced immune-mediated fetal injury, the impacts of maternal CD4 and CD8 T cell depletion prior to Lm infection on pregnancy outcomes were evaluated." (PMID 22916020, 2012). "Even the anti-CD4-BS neutralizing activities of plasmas isolated later in infection, which were broader and more potent, were ineffective against these and other viruses." (PMID 23152926, 2012). "Immediately after infection the viral load increases with exponential growth kinetics and CD4+ T cells rapidly decline." (PMID 22754568, 2012). "IFNγ-producing CD4+ T cells are recruited to this site during challenge infection potentially mediating parasite killing via classical activation of macrophages producing iNOS via an IFNγ and TNFRI-dependent pathway." (PMID 22360486, 2012). "Within the first 7 days of infection we were able to detect significantly higher numbers of CD4+, CD8+ and γδTCR+ cell populations that were positive for IFN-γ in both the lung and spleen compared to uninfected controls." (PMID 22428026, 2012). "In the infection with MT forms cytokine production by CD4+ and CD8+ led to an early production of IFN-γ and only later there was an increase in the production of TNF-α." (PMID 22412949, 2012). "The C7 deficient mice had markedly reduced lung occlusion with significantly increased total lymphocytes, decreased macrophages, and increased numbers of CD4+ cells 60 days post-infection." (PMID 22973398, 2012). "CD4+ cells stimulated with Mtb complex showed enhanced infection with R5- and X4-tropic HIV, compared to unstimulated cells or cells stimulated with M. smegmatis (p<0.01)." (PMID 22844428, 2012). "To further show that secretion of IFNγ is impaired in CD4+ T cells during infection, we measured STAT1 phosphorylation in dLN CD4+ T cells of L. major-infected N1N2ΔCD4Cre mice." (PMID 22396647, 2012). "Very interestingly, H-1 PV is even able to enhance activated CD4+ T cell ability to release IL-2 right from the beginning of the infection, and IL-4 at early and late infection stages (24 h and 120 h after the inoculation)." (PMID 22359669, 2012). "CD4+ and CD4− T cells were isolated from the blood of three sheep at different times between one and nine weeks after infection to assess their capacity to be activated by CD1b+ L-DCs primed in vitro with Salmonella (data not shown)." (PMID 22279590, 2012). "In the absence of IL-7 treatment, SIV infection caused significant decreases in the absolute numbers of naïve and memory CD4+ T cells, compared to pre-infection levels, throughout the acute phase of the infection." (PMID 22511868, 2012). "B cells are the primary targets of MDV at the early cytolytic stage of the disease and infection of these cells by the virus leads to activation of CD4+ T cells which are more vulnerable to infection than naive T cells." (PMID 23029045, 2012). "Our results suggested that specific cell subsets including B cells, CD4+ T cells, and macrophage/monocytes are specifically modulated by the infection, in comparison to uninfected patients." (PMID 22229039, 2012).
infection (continued). "Wt mice had mild disease and infection, mounting a sufficient early innate response and a subsequent influx of activated CD4+ and CD8+ T-cells, effective release of Chlamydia-specific IFNγ and proliferation of mediastinal lymph node T-cells." (PMID 22724018, 2012). "Systemically, infection with wild type LAI at this high dose resulted in near total depletion of CD4+ T cells in all tissues analyzed and double-positive thymocytes as well." (PMID 22640559, 2012). "A decrease in the frequency of CD4+CD8+ T cells was statistically significant at day 2 post-infection in infected pigs compared to their levels at preinfection." (PMID 22340040, 2012). "In the present study, we observed that the percentage of CD4+ T cells or the ratio of CD4/CD8 in yellow cattle was significantly higher than those in water buffalo from pre-infection to 7w post infection." (PMID 22414188, 2012). "Persistent HBV infection is mainly due to inefficient CD4+ T cell priming early in the infection and subsequent development of a quantitatively and qualitatively ineffective CD8+ T cell responses." (PMID 23227158, 2012). "TLR2 signaling also enhances infection of quiescent naïve and memory CD4+ T cells, which are normally relatively resistant to HIV infection." (PMID 22844428, 2012). "On the other hand, activated CD4+ T cells (effector) produce high viral-load levels, generating high viral gradient in the mucous membrane tissues, resulting in infection amplification and spread over long distances." (PMID 23101545, 2012). "They showed that the minor allele of one tagSNP was associated with higher CD4 T-cell count, lower viremia and reduced LEDGF/p75 mRNA expression during early infection and slower CD4 decline during the chronic phase." (PMID 23226247, 2012). "In Pneumocystis, although antibodies play a role in protection, cellular immune responses, especially CD4+ T cell responses, are critical for clearing infection and providing protective immunity." (PMID 22788748, 2012). "With seven of these infections, there were at most small drops in the levels of CD4+ T cells in peripheral blood; but with three mice substantial drops in CD4+ T cells were observed." (PMID 22640559, 2012). "Up to four-fold increased infection of hPBMCs by stock SIV in the presence of anti-CD4 mAb, seen in several experiments, was probably due to more efficient envelope binding of partially capped, actin associated CKRs following Leu3a cross-linking of CD4." (PMID 22830620, 2012). "The increase in peripheral CD4+ T cell counts to the level of counts in HIV-1 uninfected individuals depended on initiating HAART during the acute/early stage of infection." (PMID 22241988, 2012). "For the CD4+ T lymphocyte compartment, the model begins with the assumption of about 3.5×109 total CD4+ T lymphocytes at baseline before infection in a macaque, of which about 99% are in a resting state." (PMID 23028619, 2012). "As more than 95% of the reservoir is harbored by CD4+ T cells (Chomont N, unpublished data), we estimated the frequency of infection of CD4+ T cells in the blood based on their percentage among PBMCs (measured by flow cytometry)." (PMID 22479485, 2012). "Nonetheless, despite lack of N283, we found low CD4 dependence of the LT5.J4b Env, thus highlighting role of other compensatory determinants conferring efficient infection of low CD4 expressing cells." (PMID 23056416, 2012). "From 2010, in some selected regions, including XUAR, free treatment was provided from diagnosis for those with CD4 between 350 and 500 (on average two years after infection)." (PMID 22839738, 2012). "Macaques with lower pre-infection NKT frequencies showed a significantly greater CD4+ T lymphocyte decline post SIV infection." (PMID 23028326, 2012).
infection (continued). "In ex vivo human tonsil cultures infected with HIV-1, it was shown that over 95% of the dying CD4+ T cells were bystanders, with the vast majority being resting CD4+ cells which had undergone abortive infection, inducing cell death." (PMID 23170164, 2012). "Infection with C/R viruses and T/F viruses resulted in the significant depletion of tissue CD4 T cells." (PMID 23236398, 2012). "Using the PECA-SI algorithm, we detected 323, 129 and 107 differential splicing events in transcripts of virus-infected versus uninfected bystander CD4+ T cells at 24, 48 and 72 h post-infection, respectively (see Methods for filtering parameters)." (PMID 22876188, 2012). "During acute HIV-1-infection, massive losses of CD4+ T cells occur in gastrointestinal tissues, perhaps due to the increased sensitivity of these cells to Env-mediated autophagic cell death." (PMID 22606989, 2012). "We found in this report a higher frequency of CXCR3+ among CD4 T cells in the acute DENV-infection, while a similar proportion of the CXCR3+ among CD8 T cells was detected in DENV-infected patients as compared to controls." (PMID 22815692, 2012). "In CD4+ T cells, the viral replication is dependent upon the cell cycle of the host cell and HIV-1 entry into activated CD4+ T lymphocytes leads to productive infection." (PMID 22548060, 2012). "DCs can be directly infected by HIV (cis-infection), although the frequency of in vivo infected DCs is 10- to 100-fold lower than that of infected CD4+ T cells." (PMID 22912740, 2012). "Another aspect is the fact that infection with HIV leads to redistribution of CD4+ cells between blood and lymphatic tissue." (PMID 22474480, 2012). "In the course of these repeated infections, P. falciparum-specific CD4+ T-cells develop and play a critical role in ameliorating morbidity and mortality." (PMID 22745697, 2012). "Among the combination regimens fludarabine in combination with alemtuzumab (FluCam regimen) was first given to refractory CLL patients, showing that most infections occurred within the first 3 months, when CD4+ cells were at the lowest level." (PMID 23205258, 2012). "We find that, in the setting of low viral load, the lifespan of infected cells is very long, whereas during active infection there is a surprisingly high turnover of viral DNA within resting CD4 T cells." (PMID 22496643, 2012). "The gastrointestinal immune system, in particular, is an important target of HIV/SIV as it is not only the largest immunologic organ but also a major site for viral replication and CD4+ T cell destruction (as early as 21 days post infection)." (PMID 22511950, 2012). "A significant finding of this study is the inconsistent clinical parameters of high viral load and high CD4 count co-existing in over half the adolescents studied, where the duration of infection is >10 years." (PMID 23171203, 2012). "Macrophages and dendritic cells, B cells and CD4+ T cells have been shown to produce IL-10 during this infection, though their contributions to IL-10 production in acutely infected livers remain to be examined." (PMID 22880122, 2012). "Some variants of HIV-1 can use either co-receptor (dual/mixed-tropic [DM] HIV-1); these can be found in all stages of infection, but are more common in infections of longer duration, with lower CD4+ cell counts and higher viral loads." (PMID 22281097, 2012). "This maximum density was 200 cells/μL, and this particular value agrees with previous infection models based on activated CD4+ cells." (PMID 23217087, 2012). "CD4+/CCR5high/ α4β7high T cells are highly susceptible to infection by HIV-1 and are ideal targets for an efficient productive infection at the point of transmission." (PMID 21284901, 2011). "We find that after inoculation in vitro, even at very low multiplicities of infection, ES CD4+T cells have similar integration efficiencies compared to normal donors." (PMID 21383972, 2011).
infection (continued). "This phenotypic observation fits with parallel studies in human mucosal tissue explants and studies delineating the initial target cells of infection in the macaque model, all of which implicate CD4 T cells as the initial targets for infection." (PMID 21284905, 2011). "This is an interesting finding because it is generally accepted that non-conventional CD4+ T cells, such as NKT cells, are particularly shaped for early immune responses to infections while conventional CD4+ T cells are responsible for acquired immunity." (PMID 21814579, 2011). "The most significant barrier is the establishment of a latent or "silent" infection in resting CD4+ T cells." (PMID 21255462, 2011). "The transient depletion of CD4 T cells at the time of infection with LCMV clone 13 results in life-long viremia and high viral titers throughout the mouse." (PMID 21814510, 2011). "It was further shown that SIV-specific CD4+ T cells recognize and inhibit viral replication very early after infection of a cell." (PMID 21326882, 2011). "It is well established that CD4+ T cells play an important role in immunity to infections with retroviruses such as HIV." (PMID 21943070, 2011). "CD8+ T cell depletion resulted in a drastic reduction of the relative and absolute number of LCMV-specific CD4+ T cells producing IFNγ and TNFα on day 8 and 11 after infection." (PMID 21966366, 2011). "Our results are consistent with the possibility that CD8 T cells are involved in the immune “deviation” of CD4 T cells and that this is involved in the development of protection against infection." (PMID 21695103, 2011). "Group B showed more variation, in particular B209 which exhibited a precipitous drop in CD4 counts after 20 weeks SIVsmE660 infection, comparable to unvaccinated challenge controls." (PMID 21853072, 2011). "We wanted to investigate in details the effect of prolonged treatment started in early infection on HIV-1-specific CD4+ T-cells as these cells play a central role in sustaining CD8+ T-cell functions." (PMID 21483676, 2011). "When CD4 T cells are transiently depleted at the time of infection with LCMV clone 13, the mice become viremic for life in contrast to untreated mice that control viremia in 2–3 months." (PMID 21814510, 2011). "At least with LCMV Armstrong infection, CD4 T cell help appears to be intact as CD8 T cell memory cells are fully functional upon secondary challenge." (PMID 21814510, 2011). "We show that R5 viruses evolved early in two rapid progressor macaques to become sCD4-sensitive, and this correlated with better gp120 binding to CD4 and with efficient infection of CD4low cells such as primary macrophages and the HeLa RC49 cells." (PMID 21760891, 2011). "The strong Tfh differentiation of FV-specific CD4+ T cells can be a result of the specific cytokine environment that this infection creates, as it is likely to be the case for Th1 differentiation." (PMID 21943070, 2011). "Spleen and lymph node cells from mice were pooled for quantification of 2W:I-Ab-specific CD4+ T cells by pMHCII-based cell enrichment at various times after infection with GAS-2W." (PMID 21966268, 2011). "Similar to primary infections, CD4+ T-cell declines were observed starting on day 17 PI in FIV-C36 cats which persisted until day 138 PI." (PMID 21887365, 2011). "Because CXCR4 is the infection receptor for the CD4-indepndent infection of the mNDK vector, cell surface expressions of CXCR4 in these cells were analyzed." (PMID 21541353, 2011). "Throughout the first five days of secondary infection, there was a modest three-fold increase in CD4+ cell recovery from the draining mediastinal lymph node (MLN)." (PMID 21647373, 2011). "This is a relevant limitation of the CD8+ T cell-depletion experiments, and therefore a role of CD4+ T cells in the induction of immunopathology during LCMV-infection cannot be excluded." (PMID 21966366, 2011).